PTK7 (protein tyrosine kinase 7 (inactive))
Diseases named in the same sentence as PTK7 in open-access papers (continued):
Sharing a sentence is not in itself a finding about the gene and the disease.
tumor (continued). "Our findings demonstrate that PTK7-neutralizing mAbs effectively inhibit tumor growth, migration, invasion, and EMT in TNBC models, establishing them as a promising therapeutic option." (PMID 39936972, 2025). "PTK7 is frequently overexpressed in BC and correlates with poor clinical outcomes, including increased tumor size, lymph node metastasis, and reduced survival." (PMID 39936972, 2025). "For example, cofetuzumab pelidotin (PF-06647020), a PTK7 mAb conjugated to a microtubule inhibitor via a cleavable linker, has demonstrated strong anti-tumor activity." (PMID 39936972, 2025). "Cy5-Sgc8c-M demonstrated obvious colocalization with PTK7 proteins in both cells and xenograft tumor sections." (PMID 40987771, 2025). "Targeting PTK7 with ADCs has shown considerable promise, particularly in reducing tumor-initiating cells and inducing tumor regression, including patient-derived xenografts." (PMID 39936972, 2025). "MTX-13, a novel PTK7-directed ADC, has demonstrated anticancer activity and the ability to overcome tumor resistance in pan-PTK7+ tumors and has the potential to outperform PF-06647020 in clinical trials." (PMID 39474113, 2024). "In vivo, PTK7-targeting CAR-T cells induced significant inhibition of tumor growth and prolonged overall survival in xenograft tumor models of lung cancers." (PMID 38773263, 2024). "We did, however, observe an association between PTK7 mRNA expression and the survival of patients with ER-positive (p = 0.020), PgR-negative (p = 0.002), and HER2-negative tumours (p < 0.001) in the METABRIC cohort." (PMID 39335176, 2024). "We determined PTK7 expression in patient tumours using immunohistochemistry and assessed PTK7 mRNA expression in the METABRIC and TCGA cohorts." (PMID 39335176, 2024). "In essence, FOXP4 emerges as a pivotal transcriptional target within the Wnt/β-catenin/TCF4 signaling axis, regulating the downstream transcription factor PTK7 and thereby fostering tumor proliferation, migration, and invasiveness." (PMID 38740744, 2024). "The value of PTK7-targeted aptamers in detecting circulating tumor cells (CTCs) has also been consistently demonstrated." (PMID 39474113, 2024). "In vivo experiments also confirmed that PTK7 depletion slowed tumor growth and prolonged the survival of tumor-bearing mice." (PMID 39474113, 2024). "BCG033 candidates showed potent anti-tumor activity in several PTK7/TROP2 co-expressing cell line-derived xenografts." (PMID 39474113, 2024). "In line with this, a first-in-human study to evaluate PF-06647020 in patients with solid tumors (NCT02222922) showed that in responders, PTK7 was moderately or strongly expressed in the tumor." (PMID 39065798, 2024). "As for serous cancer, PTK7 expression was associated with lower Who’s grade and MDACC’s grade in addition to tumor clinical stage." (PMID 39474113, 2024). "In this study, there were significant associations between high PTK7 protein expression and grade, higher NPI group, ER- or PgR-negative tumours, HER2-positive tumours, and triple-negative tumours." (PMID 39335176, 2024). "This was supported by the observation that high PTK7 mRNA expression was significantly associated with higher NPI groups, ER- or PgR-negative tumours, and HER2-positive tumours in the METABRIC cohort." (PMID 39335176, 2024). "The downregulation of PTK7 inhibits the formation and function of invadopodia, which is capable of promoting tumor metastasis and dissemination." (PMID 39474113, 2024). "Comparative analysis revealed significantly higher PTK7 levels in cancerous versus non-tumor tissues." (PMID 39397032, 2024). "The normalised enrichment scores (NES) with a false discovery rate of less than 1% identified 3/50 enriched gene sets in tumours with high expression of PTK7 and 4/50 in tumours with low expression of PTK7." (PMID 39335176, 2024).
tumor (continued). "The top 20 targets highly upregulated in tumor compared to all NT (ranked according to the log2(FC) T vs CT) include transcripts encoding for COL11A1, TNC, PTK7, and P4HA3." (PMID 39681068, 2024). "For this study, we selected PTK7 as an alternative recognition site for tumor cells that had lost CD19 antigens." (PMID 38148412, 2024). "Taken together, these results suggest that PTK7 plays a critical role in facilitating FOXP4’s tumor-promoting effects in OV cells, highlighting the importance of PTK7 suppression in this context." (PMID 38740744, 2024). "FOXP4 functions as a transcriptional target of Wnt/β-catenin/TCF4, facilitating PTK7 transcription and thereby fostering OV tumor development and advancement." (PMID 38740744, 2024). "The undeniable potential risk was that the new targeting effect would likewise be attenuated or even off‐target again as the expression of PTK7 on tumor cells declines." (PMID 38148412, 2024). "Many studies have displayed successful anti-tumour activity in vitro and in vivo using CAR-T cells specific to NSCLC tumour-associated antigens such as B7-H3, GD2 and PTK7." (PMID 37296957, 2023). "Here, we showed that tumor tissues from BC patients had significantly higher PTK7 mRNA levels than normal tissues." (PMID 37569547, 2023). "The Dox‐loaded sgc8‐eNC specifically recognizes PTK7‐positive tumor cells and exclusively internalized into tumor tissues via receptor‐guided endocytosis." (PMID 36253152, 2022). "Tumor weights were also significantly reduced to 77.6 ± 8.5% by PTK7 mAb-32 and to 67.2 ± 12.9% by PTK7 mAb-43, compared with that of the vehicle group." (PMID 36293051, 2022). "The PTK7-GEMs-treated group displayed an enhanced inhibitory effect against tumor metastasis compared with that of the GEM-treated or LIB-GEMstreated groups." (PMID 36471380, 2022). "In a mouse xenograft study using KYSE-30 cells, we observed that the PTK7 mAb-treated group had significantly reduced tumor volume and weight compared with that of the vehicle group." (PMID 36293051, 2022). "The tumor weight decreased to 73.8 ± 5.2% and 31.7 ± 8.6% in PTK7-knockdown tumors with PTK7-KD-6433 and PTK7-KD-6434, respectively, compared to the tumor weight (0.73 ± 0.08 g) of the mock control tumors." (PMID 35216506, 2022). "Hematoxylin and eosin staining and immunohistochemical staining for PTK7 and Ki-67 were performed on the tumor sections to assess changes in cell morphology and proliferation." (PMID 35216506, 2022). "Hematoxylin and eosin (H&E) staining of tumor tissue demonstrated the most obvious nuclear condensation and vacuolation in the PTK7-GEMs group, suggesting higher levels of apoptosis and cell death." (PMID 36471380, 2022). "After injection of PTK7 mAbs, inflammation was detected at the tumor sites in some mice, particularly in the vehicle group." (PMID 36293051, 2022). "These molecules provide unique therapeutic targets as demonstrated by an antibody–drug conjugate against the Wnt signalling PTK7 tyrosine kinase molecule, which elicited potent anti-tumour activity in low-passage patient-derived solid tumour xenograft models." (PMID 34728792, 2022). "In a mouse xenograft model of ESCC using KYSE-30 cells, PTK7 mAbs reduced tumor growth in terms of volume, weight, and the number of Ki-67-positive cells." (PMID 36293051, 2022). "Nevertheless, tumor volumes were significantly reduced to 68.8 ± 5.3% by PTK7 mAb-32 and to 61 ± 7.7% by PTK7 mAb-43, compared with that of the vehicle group." (PMID 36293051, 2022). "Our RNA-seq analysis of HGSC tumor samples identified decreased PTK7 expression in post-NACT samples but the expression was elevated in relapsed samples." (PMID 35977930, 2022). "Both PTK7 mAb-32 and PTK7 mAb-43 showed statistically significant anti-tumor activity at the cellular level and in vivo compared to the control." (PMID 36293051, 2022).
tumor (continued). "The sgc8 is an aptamer capable of binding to a particular transmembrane protein PTK7 overexpressed in many tumor cells (e.g., CEM and HeLa cells) and installed at the vertex of DNA Tetra unit." (PMID 36253152, 2022). "In this regard, we developed mAbs that recognize the extracellular domain of PTK7 and analyzed their anti-tumor effects." (PMID 36293051, 2022). "A TNBC tumor bearing mouse model was established to further analyze the role of PTK7 in TNBC tumorigenicity in vivo." (PMID 34367983, 2021). "Although some lines of evidence revealed the important role of PTK7 in tumor progression, the molecular functions of PTK7 in metastasis and motility in TNBC remains elusive." (PMID 34367983, 2021). "One transmembrane protein that is most likely involved in this process is protein tyrosine kinase 7 (PTK7), an evolutionary conserved Wnt co-receptor that is expressed in cranial NC cells and several tumor cells." (PMID 34502237, 2021). "Again, PTK7-CAR2 T cells exhibited a trend of more potent proliferation when stimulated with tumor cells expressing a lower level of PTK7." (PMID 34475869, 2021). "Firstly, two probes, radio- and fluorescent-probe, were in vitro evaluated verifying the high specific PTK7 recognition and its internalization in tumor cells by the endosomal route." (PMID 34620894, 2021). "When dividing TNBC tumor samples into groups based on PTK7 IHC staining score, the percentage of high PTK7 expression samples was significantly higher in TNBC with TNM stage III and lymph node metastasis groups." (PMID 34367983, 2021). "In contrast, mice treated with control T cells or PBS developed a rapidly progressive tumor, necessitating euthanasia approximately 6 weeks after tumor inoculation, excluding the contribution of allogeneic reactivity to antitumor effect of PTK7-CAR T cells." (PMID 34475869, 2021). "Noticeably, PTK7-CAR2 T cells demonstrated a comparatively higher degree of cytotoxicity against tumor cells expressing the lower level of PTK7 (H69, BxPC3, and H1299 cells)." (PMID 34475869, 2021). "T-cell proliferation was dependent on the expression level of PTK7 on target cells, and tumor cells with a high level of PTK7 expression induced more vigorous T-cell proliferation than that with a lower level of PTK7 expression." (PMID 34475869, 2021). "The group 1 TK DDR2 has been implicated recently in immune evasion by BCa tumors, whereas targeting PTK7 (also a group 1 TK) has been reported to induce regression of several tumor model systems." (PMID 34292953, 2021). "As PTK7 has be reported to be shed from tumor cells in a soluble form, we also evaluated the effect of soluble PTK7 on the cytotoxicity of PTK7-CAR T cells, which showed it minimally impacted the tumor killing of these cells." (PMID 34475869, 2021). "We next evaluated the specific killing of PTK7-positive tumor cells by PTK7-CAR T cells in both short-term (18 h) and recursive long-term (three rounds with each round of 3 days) cytotoxicity assays." (PMID 34475869, 2021). "The poor outcome seen with PTK-7 overexpression provides an argument to discuss the potential benefits of adjuvant treatment after curative tumor resections." (PMID 31820857, 2020). "Aptamer sgc8c is a short DNA sequence that can target protein tyrosine kinase 7 (PTK7), which was overexpressed on many tumour cells." (PMID 30311693, 2019). "PTK7 was shown to be overexpressed in tumors vs. normal tissues, and enriched in CSCs of different tumor types." (PMID 30984612, 2019). "PTK7 expression within each tumor is heterogeneous, and the extent of heterogeneity varies from tumor to tumor." (PMID 30984612, 2019). "While the mechanistic contribution of PTK7 to the respective tumor phenotypes is unclear at present, the upregulation of PTK7 in many tumor types makes it an attractive tumor marker and therapeutic target." (PMID 28424771, 2017). "When PTK7 expression was disrupted by RNAi, the tumor cells proliferated slowly and became prone to apoptosis." (PMID 28545451, 2017).
tumor (continued). "To evaluate the role of PTK7 in tumor invasion, we compared the migration of siPTK7and siControl cells in vitro." (PMID 28545451, 2017). "Recently, we demonstrated that PTK7 displays phenotypes ranging from oncogenic to tumor-suppressive depending on its concentration relative to those of its binding partners, such as kinase insert domain receptor (KDR)." (PMID 27689325, 2016). "In a previous report, we described increased PTK7 expression in tumor tissue of ESCC patients and its correlation with poor prognosis." (PMID 27689325, 2016). "Although MMP9 induction is controlled by various stimuli and signaling pathways, we have shown that PTK7 expression is positively correlated with MMP-9 expression in samples of ESCC tumor tissue from 155 patients." (PMID 27689325, 2016). "Consistently, xenotransplantation of human PTK7-depleted CRC cells resulted in significant reduced tumor growth and a trend toward less metastatic events, compared to control cells." (PMID 25962058, 2015). "Using a cut-off of at least 10% of positive cells with an intensity of 2 or more (which will be used thereafter as definition of PTK7 overexpression), 47 patients had detectable PTK7 overexpression in tumor tissue (34%) but only 3 in normal mucosa (2%)." (PMID 25962058, 2015). "Mean tumor volumes in PTK7-specific siRNA-treated mice were reduced in comparison with those of the control mice." (PMID 24587299, 2014). "In a xenograft nude mouse model, PTK7 siRNA resulted in a reduction of the tumor size, compared with scrambled siRNA injection." (PMID 24587299, 2014). "Silencing of PTK7 dramatically suppressed tumor formation in the xenografts of the nude mice (P<0.01)." (PMID 24587299, 2014). "In univariat analysis significant differences in PTK7 expression for tumor size (ANOVA, p = 0.033) in BC and nodal status (ANOVA, p = 0.007) in LN (higher expression level with number of LN metastasis) was seen." (PMID 24409301, 2014). "Furthermore, MTX-13, another PTK7-targeting ADC carrying the topoisomerase I inhibitor exatecan, demonstrated sustained tumor regressions across a broader range of PTK7-positive tumors, suggesting its expanded therapeutic potential." (PMID 39936972, 2025). "However, it was unable to induce sustained tumor regression, as was observed in the PTK7-positive NCI-H1975 model." (PMID 40987771, 2025). "PTK7-targeting CAR T cells induce tumor cell death in vitro and in vivo." (PMID 39474113, 2024). "Translational and clinical studies support the implication of PTK7 in tumor development and metastatic dissemination and its suitability as a new therapeutic target using antibody-based strategies, antibody-drug conjugates (ADCs), and chimeric antigen receptor-modified T cells (CAR-T cells)." (PMID 38773263, 2024). "PTK7 mediates tumor radioresistance by affecting NF-κB-dependent apoptosis." (PMID 39474113, 2024). "Instead, it enhances their specific localization at PTK7-overexpressing tumor tissues." (PMID 39397032, 2024). "PTK7 depletion slows tumor growth and prolongs tumor-bearing mice survival in vivo." (PMID 39474113, 2024). "Meanwhile, PTK7 also has the property of promoting tumor growth in mice." (PMID 39474113, 2024). "Collectively, these results confirm the hypothesis that the Sgc8-c aptamer acts as a tumour-specific vehicle for dasatinib, binding to PTK7 and delivering the drug into the cell, enhancing its biological activity." (PMID 36765879, 2023). "Using in vitro cytotoxicity assays, they found that their PTK7-targeted CAR T treatment was effective through multiple rounds of tumor challenge, and using in vivo xenograft mouse models, they found that their therapy suppressed tumor growth and increased overall survival." (PMID 37998743, 2023). "PTK7 is a tyrosine kinase in the non-canonical Wnt signaling pathway considered a potential tumor-associated antigen target for CAR T therapy in NSCLC, due to its high expression in cancer stem cells in multiple solid tumors, including NSCLC." (PMID 37998743, 2023).
tumor (continued). "Furthermore, PTK7-targeted antibody–drug conjugates exhibited a decrease of tumor-initiating cells and induced tumor regression." (PMID 37569547, 2023). "Moreover, the expression of PTK7 in tumor-initiating cells from xenograft tissues derived from TNBC patients was higher than that in normal tissues." (PMID 37569547, 2023). "This confirmed that PTK7 promotes tumor progression in ESCC." (PMID 35216506, 2022). "Earlier studies pointed towards a tumor suppressor role for PTK7 in OC, while recent clinical data from PTK7 targeting with the antibody-drug conjugate cofetuzumab-pelidotin showed promising outcomes in phase I clinical trial for solid tumors, including chemoresistant OC patients." (PMID 35977930, 2022). "Furthermore, PTK7-GEMs showed stronger anti-tumor efficacy and excellent biosafety in three types of tumor xenograft mice models." (PMID 36471380, 2022). "In addition, the PTK7-GEMs group displayed the weakest staining for the Ki67 antigen (brown), which indicates the greatest anti-tumor effect of PTK7-GEMs." (PMID 36471380, 2022). "Furthermore, PTK7 mAbs significantly reduced tumor growth and Ki-67 expression levels in xenograft tumor mice of KYSE-30 cells." (PMID 36293051, 2022). "Moreover, PTK7-GEMs showed stronger anti-tumor efficacy and excellent biosafety in three types of tumor xenograft mice models." (PMID 36471380, 2022). "Immunohistochemical (IHC) staining for PTK7 and Ki-67 proteins was performed on tumor sections." (PMID 36293051, 2022). "However, PTK7 also acts as a tumor suppressor in some cell types, such as epithelial ovarian carcinoma and lung squamous cell carcinoma cells." (PMID 35216506, 2022). "In addition, tumor growth was reduced by PTK7 knockdown in a xenograft model of ESCC using KYSE-30 cells." (PMID 36293051, 2022). "The clinical effect of PF-06647020 correlated with PTK7 expression in tumor tissues." (PMID 36618922, 2022). "Although CCK-8 and cell cycle experiments showed that GEM and PTK7-GEMs had similar cytotoxicity toward 5637 cells in vitro, PTK7-GEMs showed a better anti-tumor effect in vivo, which might be explained by better targeting of PTK7-GEMs in vivo." (PMID 36471380, 2022). "Up to now, aptamers have been developed for various targets such as thrombin, HBV virus, E. Coli, and other bacteria, aflatoxin B1 or M1, PSA, CEA tumor markers, or cell membrane proteins such as protein tyrosine kinase 7 (PTK7) in the CCRF-CEM T-lymphoblast membrane and others." (PMID 33494545, 2021). "PTK-7 expression was present in 66.7% of the surgical tumor specimens." (PMID 31820857, 2020). "Hence, this functionalized TDNs drug delivery system displayed its potential application in targeting PTK7‐positive tumour T‐cell acute lymphoblastic leukaemia." (PMID 30311693, 2019). "We conclude that sgc8c‐TDN is a feasible targeted drug delivery system and that s‐TDN:DOX may serve as an ideal targeted treatment against ALL or other PTK7‐positive tumours." (PMID 30311693, 2019). "In conclusion, these findings suggest that the application of s‐TDN:DOX may be a potential strategy to curb PTK7‐positive tumours such as ALL under clinical settings." (PMID 30311693, 2019). "The oncogenic role of PTK7 may be dependent on its negative regulation on apoptosis in the tumor cells." (PMID 28545451, 2017). "Indeed, the first PTK7 specific reagents with potential clinical applications have now been published, including a PTK7-specific fluorescently labeled aptamer for in vivo detection of tumor tissue." (PMID 28424771, 2017). "Indeed, disruption of PTK7 expression by siRNA rendered the tumor cells lose the proliferative advantages to the undisturbed counterparts." (PMID 28545451, 2017). "Moreover, when PTK7 was expressed, the mean percentage number of positive cells was 31% (95%CI: 25–37%) in tumor tissue versus 2% (95%CI: 1.2–3.8%; p = 5.74." (PMID 25962058, 2015). "Similarly, tumor mass was decreased by 2.6 fold in PTK7 knockdown tumors (p = 0, 0025, Mann-Whitney U test)." (PMID 25962058, 2015).